GCG (glucagon)
Diseases named in the same sentence as GCG in open-access papers (continued):
Sharing a sentence is not in itself a finding about the gene and the disease.
tumor (continued). "The present study reveals that TA effectively inhibits glucagon secretion and concurrently eradicates tumor cells, providing a novel approach for early intervention, treatment, and postoperative reinforcement of GCGN." (PMID 41150819, 2025). "Based on the suspected tumor type, laboratory tests commonly assess hormone levels such as insulin, gastrin, glucagon, vasoactive intestinal peptide (VIP), and somatostatin to identify functioning PANNETs." (PMID 40427145, 2025). "First, we have analyzed the gene expression levels of GLP1R and GCG across various normal and tumor tissues." (PMID 39777709, 2025). "We also identified the similar neural regulation of glucagon production regarding organ wasting in tumor-bearing mice." (PMID 39924534, 2025). "We further validated the conserved regulation of glucagon release in tumor-induced organ wasting in mice." (PMID 39924534, 2025). "We further revealed that the VEGFR/PDGFR signaling promotes cholinergic-α-cell interaction through ECM remodeling of α-cells in tumor-bearing ApcMin/+ mice, leading to excessive glucagon release and host wasting." (PMID 39924534, 2025). "PanNETs represent a heterogeneous group of tumours, presenting either as hormonally active tumours (producing gastrin, insulin, glucagon, somatostatin, vasoactive intestinal peptide or growth hormone-releasing hormone) or as non-functioning tumours." (PMID 39949334, 2025). "One of our important findings here includes that glucagon is essential for muscle and fat wasting in tumor-bearing mice." (PMID 39924534, 2025). "Similar to the mouse tumor model, glucagon significantly enhanced 5‐FU therapy for tumor growth suppression." (PMID 38072640, 2024). "Collectively, both in vitro and in vivo studies demonstrated that glucagon inhibited tumor angiogenesis and vascular mimicry." (PMID 38072640, 2024). "Based on the defects of directly delivering glucagon, improving the therapeutic efficacy and safety of glucagon by targeted delivery to tumor locations and selective accumulation is critical for its in vivo application." (PMID 38072640, 2024). "We carefully examined the effect of glucagon on tumor proliferation using both in vitro and in vivo models." (PMID 38072640, 2024). "As illustrated above, glucagon can inhibit tumor angiogenesis and vascular mimicry, and possesses chemosensitization capabilities." (PMID 38072640, 2024). "Glucagon is suggested to play a role in angiogenesis; therefore, we examined tumor vessels after glucagon treatment." (PMID 38072640, 2024). "Although the underlying mechanisms need further elucidation, one possibility is that glucagon impairs the migration of tumor cells, as shown in our in vitro model, thus making tube formation difficult for the tumor cells." (PMID 38072640, 2024). "Along with increased apoptosis, tumor hypoxia was also increased in the glucagon‐treated group and further increased in the combination treatment group." (PMID 38072640, 2024). "Consistent with previous data, glucagon further improved FOLFOX treatment in terms of tumor growth inhibition, as it did when combined with 5‐FU." (PMID 38072640, 2024). "The combination of glucagon and 5‐FU further decreased blood vessel and pseudo‐vessel density, which contributed to tumor growth inhibition." (PMID 38072640, 2024). "Neuroendocrine cells produce functional hormones like serotonin, insulin, glucagon, and gastrin, depending on the specific subtype of the tumor." (PMID 39211694, 2024). "Collectively, the findings demonstrate the role of glucagon in inhibiting tumor vessel network and suggest the potential utility of glucagon as a promising predictive marker for patients with CRC receiving chemotherapy." (PMID 38072640, 2024). "Inhibition of glucagon signaling with the glucagon receptor inhibitor, AL, reversed the glucagon‐enhanced tumor suppression and blood vessel regression." (PMID 38072640, 2024).
tumor (continued). "In a series of in vitro experiments, glucagon inhibited cell migration and tube formation in both endothelial and tumor cells." (PMID 38072640, 2024). "Analysis of tumor vessels revealed that glucagon not only induced blood vessel regression, but also destructively impaired vessel structure and function." (PMID 38072640, 2024). "In vivo studies demonstrated decreased tumor blood vessels and fewer pseudo‐vessels in mice treated with glucagon." (PMID 38072640, 2024). "A further interesting and potentially significant extension of this work is the liposome‐mediated tumor targeted delivery of glucagon and its acquired synergistic antitumor effect." (PMID 38072640, 2024). "Consistent with the staining results, ELISA data revealed that glucagon levels decreased significantly in the tumor tissue." (PMID 38072640, 2024). "Our exciting finding indicates the potential of glucagon as a novel endogenous antiangiogenic inhibitor which suppresses tumor growth." (PMID 38072640, 2024). "Some reports demonstrated that when the tumor is unresectable or when the operation results in an R2 resection, the administration of glucocorticoids and glucagon, chemoradiation of the primary tumor, and continuous infusion of glucose were effective." (PMID 36752872, 2023). "The remaining three RenNETs with hormonal syndrome included an insulin-secreting tumor with a hypoglycemic syndrome, a glucagon-producing tumor with a glucagonoma-like syndrome, and a tumor with a carcinoid-like syndrome." (PMID 37405461, 2023). "In time, the decline in somatostatin stops inhibiting glucagon, which then boosts ketogenesis, providing ketones to the tumor." (PMID 36836124, 2023). "Laboratory tests confirmed elevated plasma glucagon levels (>1000 pg/mL) and computed tomography (CT) scans revealed a 35/44 mm tumor in the pancreatic tail." (PMID 35054383, 2022). "GCG was found to be significantly downregulated in COADREAD tumor samples compared with healthy control samples." (PMID 35340411, 2022). "The key GCG-correlated genes, signaling pathways, and tumor immune microenvironment identified in the bioinformatics analysis require experimental evidence for validation." (PMID 35340411, 2022). "Of tumor-bearing animals, only one male exhibited a 2.3-fold elevation of plasma glucagon, less than 1% of the total population and within the natural expected Gaussian distribution." (PMID 34862365, 2021). "All PanNETs examined expressed insulin in the tumor mass and a few also exhibited expression of glucagon and somatostatin." (PMID 34862365, 2021). "While only a subset of ARX+ tumours secreted glucagon (n = 7, 20% of all the ARX+ tumours), almost all the PDX1+ tumours produced insulin (n = 18, 95% of all PDX1+ tumours)." (PMID 33288854, 2020). "The clinical presentation of functioning tumours depends on the peptide hormone being secreted such as insulin, gastrin, glucagon, vasoactive intestinal peptide (VIP) and somatostatin." (PMID 31447997, 2018). "Of the other five lesions, two tumors consisted of the insulin-positive tumor cells with less than 0.1 % of the Ki67 index, and three tumors consisted of the glucagon-positive tumor cells with less than 0.1 % of the Ki67 index." (PMID 27572829, 2016). "Immunohistochemical examination revealed that liver metastases were derived from a glucagon-positive tumor of the pancreatic NET." (PMID 27572829, 2016). "As these α-cells are the main source of glucagon and tumor-bearing LSL-MYCN;hGFAP-Cre mice displayed with elevated blood glucagon levels as well as Glucagon-positive tumors, these findings are in line with the diagnosis of a glucagon-producing PanNET." (PMID 27769070, 2016). "The diagnosis of this rare tumor requires an elevated serum glucagon level and imaging confirming a pancreatic tumor." (PMID 25029913, 2014).
tumor (continued). "Various mechanisms were proposed are: (a) insulin or insulin-like activity produced by the tumour, (b) decreased gluconeogenesis, (c) disruption of glucagon metabolism, and (d) increased utilization of glucose by the tumour." (PMID 24741994, 2014). "Immunohistochemistry of the primary tumour a year prior revealed focal positivity for serotonin, as well as insulin, glucagon, and pancreatic polypeptide." (PMID 23476666, 2013). "When the glucose availability in perinecrotic regions of a micro tumor cord was increased through continuous administration of glucagon by using an osmotic pump, the expression of HIF-1α in these regions was significantly increased." (PMID 23203043, 2012). "Laboratory data, including measurement of tumor markers, were within the normal ranges, and her insulin and glucagon levels were also within the normal ranges." (PMID 20825631, 2010). "Laboratory data, including tumor markers, were within the normal ranges, and her insulin and glucagon levels were also within the normal ranges." (PMID 20825631, 2010). "One other apparent discrepancy between the clinical diagnosis and hormone expression profile occurred with tumor 11, which had high a level of glucagon expression." (PMID 15691381, 2005). "Measuring plasma glucagon levels helps in excluding this tumor from the differential diagnosis." (PMID 40291307, 2025). "In summary, this study expands our understanding of glucagon’s role in pNET pathophysiology, emphasizing the significance of metabolic regulation in tumour adaptation and highlighting GCGR as a key candidate for future biomarker development and targeted therapy." (PMID 40649254, 2025). "This exploration aims to establish a foundation for the development of safe and efficacious drugs that not only modulate glucagon secretion but also eliminate tumor cells, and further contributes for the management of GCGN by presenting novel targeted drugs and therapeutic strategies." (PMID 41150819, 2025). "Considering that all pancreatic pNETs arise in the Langerhans islets, whose microenvironment is glucagon-rich, and understanding how glucagon promotes tumour survival and metabolic remodelling in pNETs may provide insights into new therapeutic targets." (PMID 40649254, 2025). "To explore targeted therapeutic drugs that can inhibit glucagon secretion and tumor proliferation, we investigated the effect of Trametenolic Acid (TA) on mouse pancreatic alpha TC1 clone 6 (αTC1-6) cells and its regulatory role in the PI3K/AKT signaling pathway." (PMID 41150819, 2025). "However, indirect parameters (low IGF‐I, low insulin/C‐peptide, positive glucagon test) and clinical resolution post‐tumour excision strongly support the diagnosis." (PMID 40697895, 2025). "Interestingly, we also confirmed the similar mechanisms governing tumor-induced glucagon release and organ wasting in mammals." (PMID 39924534, 2025). "Increased abundance of glucagon (GCG) was observed in tumor samples P3 and P6." (PMID 40217502, 2025). "To do this, we first assessed the glucagon changes in tumor-bearing mammals." (PMID 39924534, 2025). "In cases of unresectable or metastatic disease, cytoreductive surgery (debulking) or liver-directed locoregional therapies—such as embolization, radioembolization, or ablation—may reduce tumor burden and glucagon secretion." (PMID 40647278, 2025). "Pancreatic CT is very useful for determining the precise location of the tumor, its relationship with surrounding organs, and metastatic status; glucagon level measurements are definitive for diagnosis; and the high expression of pancreatic somatostatin receptors is also crucial in diagnosis." (PMID 39252948, 2024). "To confirm our hypothesis, we established a glucagon overexpressed tumor cell line, OE‐GCG‐CT26, to test whether endogenous glucagon would show the same antitumor effect as 5‐FU." (PMID 38072640, 2024).
tumor (continued). "Longer treatment period with glucagon alone to the tumor model may exhibit a stronger antiangiogenic effect and finally resulting tumor growth retardation." (PMID 38072640, 2024). "Thus, glucagon inhibited vascular mimicry, which contributed to tumor suppression when combined with 5‐FU." (PMID 38072640, 2024). "In summary, our data provide evidence that glucagon contributes to tumor inhibition and may serve as a potential prognostic marker or therapy to enhance chemotherapy efficacy." (PMID 38072640, 2024). "Moreover, glucagon‐encapsulated PEGylated liposomes with tumor‐targeting folic acid molecules (GCG@LFA) were constructed and showed increased therapeutic efficiency in a tumor model, suggesting glucagon as a potential agent for adjuvant treatment." (PMID 38072640, 2024). "Additionally, glucagon targeted vascular mimicry, which further blocked blood supply to the tumor tissue, leading to significant tumor suppression by dual disruption of the tumor vessel system." (PMID 38072640, 2024). "In addition, a high‐fat diet‐induced diabetic mouse tumor model confirmed that elevated glucagon levels contributed to 5‐FU efficacy enhancement." (PMID 38072640, 2024). "Thus, glucagon not only impaired tumor angiogenesis but also blocked vessel perfusion and increased permeability, which blocked blood supply to the tumor tissue." (PMID 38072640, 2024). "Interestingly, combining 5‐FU or FOLFOX with glucagon treatment significantly decreased tumor cell viability." (PMID 38072640, 2024). "Moreover, staining of blood vessels with CD31 demonstrated the inhibitory effect of glucagon on tumor angiogenesis." (PMID 38072640, 2024). "In vivo, AL was administered alone or in combination with 5‐FU+glucagon to tumor‐bearing mice." (PMID 38072640, 2024). "In conclusion, glucagon could increase 5‐FU efficacy on tumor growth by inhibiting tumor angiogenesis, which blocked VEGFR phosphorylation and downstream signaling." (PMID 38072640, 2024). "As glucagon plays a role in elevating glucose levels, which may impact tumor growth, we measured the glucose levels in our mouse model." (PMID 38072640, 2024). "Surprisingly, glucagon reduced the number of pseudo‐vessels composed of tumor cells." (PMID 38072640, 2024). "Here, a new biological function of glucagon is uncovered in modulation of tumor vessels." (PMID 38072640, 2024). "The combination of glucagon and chemotherapy exhibited enhanced tumor inhibition." (PMID 38072640, 2024). "Thus, it would be interesting to elucidate the role of metabolism‐related hormones, such as glucagon, in the tumor microenvironment and determine their contribution to tumor progression." (PMID 38072640, 2024). "Additionally, the delivery of glucagon‐encapsulated PEGylated liposomes to tumor‐bearing mice amplified the inhibition of angiogenesis and vascular mimicry, consequently reinforcing chemotherapy efficacy." (PMID 38072640, 2024). "Different doses of glucagon were injected intraperitoneally into tumor‐bearing mice." (PMID 38072640, 2024). "Additionally, the potential involvement of GCG in tumor immunity was researched by investigating the correlation between GCG expression and 24 tumor infiltrating immune cells." (PMID 35340411, 2022). "The tumor cells showed moderate and diffuse glucagon staining with patchy insulin staining." (PMID 35498123, 2022). "In vivo, GCG infusion was shown to increase tumor-fractional protein synthesis in rectal cancer." (PMID 35340411, 2022). "Synthesis and growth of tumor proteins can be stimulated by glucagon in situ." (PMID 34642262, 2021). "The reason seems to be that insulin and glucagon co-expressing cells may contain cells under neoplasia, dedifferentiation and transdifferentiation into any type of islet cells." (PMID 34493754, 2021).
tumor (continued). "Many α-cells were arranged along the outer margin of the normal islet lobule, and Case 2 glucagonoma cells were weaker stained for glucagon than normal α-cells but moderately stained for CgA in 50% of individual tumor cell cytoplasm and diffusely and strongly for SPY." (PMID 32020844, 2020). "In addition, several cell lines were also established from the primary tumor which we further characterized and found to have a similar cDNA profile like the tumor samples and express chromogranin A, B, as well as secretin and glucagon." (PMID 32373532, 2020). "Immunohistochemical analyses in vivo showed that, when tumor-bearing mice were continuously administered glucagon, which increases blood glucose concentrations and so improves glucose-availability in the pimonidazole-positive hypoxic regions, HIF-1α expression was dramatically induced there." (PMID 23203043, 2012). "On immunohistochemistry, tumor cells were positive for synaptophysin, chromogranin and glucagon." (PMID 20550685, 2010). "Thus, glucagon enhances the antitumor effect of 5‐FU by destroying the tumor vessels." (PMID 38072640, 2024). "In addition, in the present study, samples with high ICC gene expression were enriched for nuclear translocation, protein localization, the glucagon signaling pathway, apoptosis, the Wnt signaling pathway and other biological processes that contribute to tumor progression." (PMID 38298057, 2024). "Interestingly, glucagon treatment inhibited cell proliferation (indicated by decreased Ki67 levels) and induced apoptosis (indicated by increased cleaved caspase‐3 levels) in the tumor tissues." (PMID 38072640, 2024). "However, the endogenous glucagon contributing to tumor growth needs to be validated." (PMID 38072640, 2024). "Although, it remains to be seen if normal hepatocytes stimulated to synthesize glucose by glucagon secretion could provide local glucose, as tumor cells are thought to regulate metabolism of others cells within the microenvironment to suit their nutritional needs." (PMID 35123542, 2022). "Infection could have been a trigger for acute decompensation, possibly aggravated by pausing antiproliferative therapy with everolimus and simultaneously enhanced demand for octreotide, which may have led to excessive tumour activity with overproduction of glucagon." (PMID 25520848, 2014). "Analysis of differential expression between GC tumor tissues and normal tissues revealed upregulated SERPINE1, IL1F10, IGFBP1, and ITIH2, whereas C6, GCG, GRP, and APOD were downregulated." (PMID 41551463, 2026). "Our study demonstrates that glucagon, through its interaction with GCGR and/or GLP-1R, plays a pivotal role in orchestrating metabolic and adaptive responses in both tumour and normal endocrine cells, particularly under conditions of glucose deprivation." (PMID 40649254, 2025). "Since GCG encodes the precursor of GLP-1, the observed reduction in GCG and other key EEC markers (CHGA, NEUROD1, PYY) in tumor tissue, combined with these external clinical data, suggests that EECs and incretin hormones may exert an anti-tumor role in colorectal carcinogenesis." (PMID 41303610, 2025). "Given the low levels of insulin, IGF‐I, and C‐peptide, combined with a positive glucagon stimulation test, the possibility of an IGF‐II–secreting tumour was considered." (PMID 40697895, 2025). "In our study, we found that glucagon suppressed vascular mimicry in CRC cells, suggesting a multi‐inhibitory effect of glucagon on the tumor vessel network." (PMID 38072640, 2024). "Functional tumours are uncommon and produce hormones and peptides including insulin, gastrin, vasoactive intestinal peptide (VIP), glucagon, somatostatin, and serotonin." (PMID 39246612, 2024). "Thus, glucagon may impair tumor vessel function, reflecting its antiangiogenic effect." (PMID 38072640, 2024).